CST3 (cystatin C)
Diseases named in the same sentence as CST3 in open-access papers (continued):
Sharing a sentence is not in itself a finding about the gene and the disease.
diabetes (continued). "Unfortunately, we have not measured creatinine in our study but there was still an increase in Cystatin C at our follow-up time (mean 1.3 years and higher levels after a longer diabetes duration." (PMID 38932813, 2024). "A longer duration of diabetes mellitus is known to be a factor that increases cystatin C levels, potentially leading to renal damage." (PMID 39125705, 2024). "In conclusion, Cystatin C levels were higher in patients with diabetes duration longer than 5 years, and inverse correlation was found between HbA1c and Cystatin C levels as well as duration of diabetes." (PMID 38932813, 2024). "The current study provides evidence indicating that diabetes, the site of MI, cystatin C, B-type natriuretic peptide, and creatine kinase-myocardial band are the primary risk factors for LVR after MI." (PMID 39560578, 2024). "The current study found positive relation between duration of diabetes and level of serum cystatin-c in diabetic patient group (p < 0.027)." (PMID 37002266, 2023). "Creatinine and cystatin C stand out as more precise markers for predicting diabetes mortality prior to blood glucose monitoring." (PMID 37775738, 2023). "This study aimed to investigate the serum cystatin C levels and dyslipidemia for the detection of diabetic nephropathy in patients with type 2 diabetes mellitus." (PMID 37082121, 2023). "For example, a 56-year-old man with a rGFR of 24 ml/min/1.73 m2 on the operative side, a rGFR of 36 ml/min/1.73 m2 on the healthy side, serum cystatin C of 0.91 mg/L, and a preoperative eGFR of 67 ml/min/1.73 m2 had a history of hypertension and diabetes." (PMID 37906264, 2023). "For diabetes individuals with a cystatin C level of less than 0.72 mg/L, the CVD mortality rate is 0.7% at 5 years, 3.9% at 10 years, 5.9% at 15 years, and 9.9% at 20 years." (PMID 37775738, 2023). "The analysis indicated that eGFR (cystatin C), diabetes mellitus, liver disease, plasma albumin level on admission, and plasma BNP level at discharge were associated with 3-year all-cause mortality." (PMID 37187794, 2023). "Multivariate logistic regression analysis showed that diabetes mellitus, baseline BNP and cystatin C levels, and contrast agent dosage were independent risk factors for CIN." (PMID 37355592, 2023). "The prevalence rates of heart disease, stroke, psychological problems, pulmonary disorders, hypertension, diabetes, and limitations in ADLs increased with increasing quartiles of cystatin C concentrations." (PMID 36564420, 2022). "Despite differential risks for diabetes and mortality by racial/ethnic groups, Cystatin-C was equally predictive of these outcomes across groups." (PMID 36094936, 2022). "We modeled diabetes and death over 8-years as function of baseline Cystatin-C (log transformed) adjusting for covariates and tested modifications in associations by race/ethnic background and sex." (PMID 36094936, 2022). "Cystatin C can be affected by conditions such as renal disease, diabetes mellitus, heart disease and thyroid disease." (PMID 35606777, 2022). "Our findings complement and expand evidence linking Cystatin-C, diabetes and mortality (treated independently) in other cohort studies, with different age ranges, race/ethnic background inclusion, and population representation." (PMID 36094936, 2022). "The results were similar even after adjustment for clinical covariates, such as blood pressure, diabetes mellitus, dyslipidemia, or urine microalbumin levels, or when genetically predicted eGFR (cystatin C) was included as the exposure." (PMID 35109828, 2022). "A better understanding of how cystatin-C influences diabetes prevalence, and potentially its onset, can have significant health and healthcare implications." (PMID 36094936, 2022). "Mortality is significantly higher among males, current smokers, and persons with: heart disease, diabetes, stroke, higher cystatin c, and higher CRP." (PMID 36284701, 2022).
diabetes (continued). "In logistic regression, both creatinine (p = 0.034) and cystatin-C (p = 0.009) were independent predictors of CVD versus diabetes plus CVD." (PMID 35996503, 2022). "Lastly, our findings address a gap in research on Cystatin-C and diabetes, particularly regarding potential differential influences by race/ethnic background and sex." (PMID 36094936, 2022). "Of the metabolic markers, only cystatin-C differed between the groups, being higher in diabetes plus CVD than in CVD alone (both p = 0.001)." (PMID 35996503, 2022). "Of the metabolic markers, only cystatin-C differed between the groups, being highest in both diabetes groups, and correlating overall with renal markers." (PMID 35996503, 2022). "There are few studies of the prognostic value of serum cystatin C in children with diabetes, yet most studies evaluated cystatin C in children with acute kidney injury." (PMID 35208542, 2022). "Prevalence of diabetes and hypertension were significantly higher among kidney transplant recipients, as were serum concentrations of creatinine, cystatin C, valine and myo-inositol, while measured GFR was significantly lower." (PMID 36465899, 2022). "Recently, the serum creatinine-to-cystatin C ratio (Scr/Scys), also known as the sarcopenia index (SI), is suggested as a surrogate marker of muscle mass in patients with type 2 diabetes mellitus (T2DM), chronic obstructive pulmonary disease (COPD) and cancer." (PMID 36419088, 2022). "Thus, Cystatin-C dysregulations could be an important predictor and early marker for diabetes risk." (PMID 36094936, 2022). "We found that serum miR‐29a and cystatin C have important clinical value in differentiating DN from simple diabetes." (PMID 34964177, 2022). "The same locus was previously reported to be associated with CKD and reduced renal function represented by both serum creatinine and cystatin c eGFR in diabetes." (PMID 36271454, 2022). "Limited work has examined links between Cystatin-C, mortality and diabetes and tested sex and race/ethnic modifications." (PMID 36094936, 2022). "Solid lines represent mean differences in serum cystatin C (mg/L) after adjusting for age, sex, race, body mass index, hypertension, and diabetes." (PMID 35722576, 2022). "Hs-CRP, eGFR by cystatin C, and ASM index were associated with serum myostatin level in men, while diabetes, eGFR by cystatin C and ASM index in women were associated with serum myostatin level." (PMID 34299795, 2021). "Further analysis found that uric acid, urea nitrogen, creatinine and cystatin C were increased and eGFR was decreased in COVID-19 patients with diabetes." (PMID 33557785, 2021). "Serum cystatin C concentration increases with the progression of nephropathy and duration of diabetes in Nepalese T2DM patients suggesting cystatin C as a potential marker of renal impairment in T2DM patients." (PMID 33996155, 2021). "PhenoAgeAccel also was genetically more correlated than BioAgeAccel with creatinine, cystatin C, HbA1c, and CRP – biomarkers linked to kidney function, diabetes, and inflammation." (PMID 34038024, 2021). "The hazard ratio simultaneously adjusted for age, smoking, diabetes, and creatinine- and cystatin C-based eGFRs was 1.26 (0.74–2.02; P = 0.41)." (PMID 34131779, 2021). "When stratified patient groups by the quartiles of Cystatin C, we found age, the proportion of male and patients with diabetes, HCY, and GS were increased in Q4 than in other quartile groups." (PMID 33466214, 2021). "Baseline serum creatinine (SCr) [odds ratio (OR), 1.006], cystatin C (OR, 1.438), lung infection (OR, 2.292), second thoracotomy (OR, 5.185), diabetes mellitus (OR, 6.868), AKI stage 2–3 (OR, 22.901) were the independent risk factors for receiving CRRT." (PMID 34888362, 2021). "In our study, statin use was nominally associated with three surrogate marker components (plasma proteins) of GrimAge: ADM, cystatin C, and TIMP-1, all of which are associated with diabetes." (PMID 34083497, 2021).
diabetes (continued). "Serum cystatin C levels were significantly higher (p < 0.05, two-tailed) in patients with diabetes mellitus (n = 43, mean 2.80 ± 1.28 mg/L) with levels ranging from 1.18–5.57 mg/L." (PMID 33401560, 2021). "Cross-sectional study including 418 men free from diabetes, aged 70–71 years and with cystatin-C estimated glomerular filtration rate (eGFR) <60 mL/min/1.73m2 and not receiving kidney-specific dietetic advice." (PMID 32514991, 2020). "The relationship between serum cystatin C levels and Gensini score, which represents the extent of multivessel disease, was investigated in the diabetes group." (PMID 32306911, 2020). "In summary, our findings demonstrate that cystatin C was significantly associated with the severity of CAD and independently predicted the presence of multivessel disease in patients with diabetes mellitus with normal renal function." (PMID 32306911, 2020). "Based on the ROC curve, a cystatin C level of 0.865 mg/L showed 67.7% sensitivity and 76.3% specificity with an AUC of 0.748 in diabetes patients for detecting multivessel disease." (PMID 32306911, 2020). "As suggested in other studies, in patients with diabetes, the use of a cystatin C-based CKD definition offered better clinical utility for risk prediction than creatinine-based equations." (PMID 33161898, 2020). "In this cross-sectional study, we found a positive relationship between the serum levels of cystatin C and multivessel disease by coronary angiography in type 2 diabetes mellitus patients with normal renal function." (PMID 32306911, 2020). "Univariate analysis showed that CKD3, CKD4, CKD5, B1 cells, B2 cells, NK cells, age, hypertension, systolic pressure, diabetes, hemoglobin, SCr, cystatin C, albumin, and triglyceride were prognostic factors for overall survival." (PMID 32266271, 2020). "The ability of cystatin C to distinguish multivessel disease patients among patients with type 2 diabetes mellitus and normal renal function was moderate." (PMID 32306911, 2020). "Cystatin C is more sensitive than creatinine especially in the detection of early kidney dysfunction among various patient groups such as diabetes, in sarcopenia, and also in the older adults." (PMID 33161898, 2020). "Meanwhile, they were more likely to be older, to be male or non-smokers, and to have higher fasting glucose, systolic BP, diastolic BP, waist circumference, LDL, cystatin C, and usage of anti-hypertensive medication, and to suffer from diabetes or CVD." (PMID 30791918, 2019). "Several studies have evaluated the reliability of formulas based on creatinine and/or cystatin-C in patients with diabetes." (PMID 31561432, 2019). "Although the present meta-analysis primarily focused on cystatin C-equations accuracy in diabetes, it is worthwhile to mention some aspects of the most widespread used creatinine-centered equations in this subset of patients." (PMID 30723243, 2019). "A PRISMA-compliant systematic review was performed in the MEDLINE and Embase databases, with “diabetes mellitus” and “cystatin C” as search terms." (PMID 30723243, 2019). "The patients in the high cystatin C group had a higher incidence of diabetes (P = 0.036) and MetS (P = 0.001), had more severe coronary artery lesion (P < 0.001), and had a higher GRACE score (P < 0.001)." (PMID 31317040, 2019). "The following variables were significantly associated with the IL‐18 concentration at three out of the four occasions during follow‐up: male sex, obesity, diabetes and biomarkers of renal function (cystatin C), and inflammation (WBC, CRP‐hs, GDF‐15, Il‐10)." (PMID 31596518, 2019). "Serum cystatin C is a sensitive indicator of early renal dysfunction and a strong independent predictor of CVD, diabetes-related mortality, and all-cause mortality." (PMID 30775381, 2019). "It has also been reported that diabetes, thyroid, acute kidney injury, cancer, and heart dysfunction can have a significant effect on blood cystatin C levels." (PMID 31352865, 2019).
diabetes (continued). "Some authors have even shown that cystatin C is a stronger predictor of cardiovascular outcomes in patients with diabetes and elderly adults than creatinine and eGFR." (PMID 29694626, 2018). "Results have often been conflicting regarding the extent of influence of lean body mass, adiposity, diabetes, smoking, level of inflammation, and thyroid function on the cystatin C concentration in blood." (PMID 29202804, 2017). "Despite having similar glucose levels, PAR-1 deficient mice developed less kidney damage after induction of diabetes, as evidenced by diminished proteinuria, plasma cystatin C levels, expansion of the mesangial area, and tubular atrophy." (PMID 27618774, 2016). "We defined diabetes as a fasting plasma glucose level ≥7.0 mmol/l or use of hypoglycemic agents, impaired kidney function as glomerular filtration rate estimated from cystatin C (eGFRcys) <60 ml/min/1.73 m2." (PMID 26753625, 2016). "The biological mechanisms behind a possible influence of the cystatin C metabolism on CVD, MetS and diabetes risk are unclear." (PMID 27218257, 2016). "This association, similar to the relation of serum Ang-2 concentrations with serum cystatin C and eGFR(cys), persists even after the exclusion of subjects with hypertension or diabetes mellitus type 2." (PMID 27893762, 2016). "Two examples of changes in assay methods involve creatinine and cystatin C. Creatinine measurement using the Jaffe method has been shown to exhibit non-creatinine chromogenic interference in samples from patients with diabetes." (PMID 26529311, 2015). "The aim of the present study was to explore the association between the cystatin C-based estimated glomerular filtration rate (eGFRcys) and the SYNTAX score (SXscore) in patients with diabetes." (PMID 24669241, 2014). "The CKD-EPI group recently published the combination of serum creatinine and cystatin C equations and other serum cystatin C-based equations which incorporated other variables such as weight or diabetes." (PMID 24868463, 2014). "Groups were similar with respect to age, gender, weight, pre-existing renal dysfunction, hypertension, medication, and baseline serum creatinine and serum cystatin C, but diabetes mellitus was significantly less prevalent in group 1." (PMID 25254489, 2014). "Mean eGFR was lower in diabetic (except by spline Log cystatin C diabetes) and hypertensive subjects by all equations." (PMID 24868463, 2014). "In humans, cystatin C levels increase with diabetes, reflecting increased glomerular filtration rates (GFR) during early renal function decline." (PMID 25428948, 2014). "Cystatin C higher than 1.2 mg/L reflected a 3-fold increased risk of LLI after adjusting for sex, age, diabetes duration, HbA1c, GA and hypertension." (PMID 23843968, 2013). "This is in contrast to the increased cystatin C level previously reported in common forms of diabetes and observed in the Polish subjects in this study." (PMID 22350134, 2013). "The purpose of this study is to explore the association between cystatin C and PAD, and to clarify its clinical value for LLI in Chinese patients who suffered from type 2 diabetes mellitus (T2DM)." (PMID 23843968, 2013). "As the concentration of cystatin C rose, the levels of age, diabetes duration, carotid and femoral IMT, systolic blood pressure, neutrophils, BUN, Cr, UA and CRP increased, but RBC, Hb, PLT, albumin, FPG, PPG and GFR decreased." (PMID 23843968, 2013). "The decline of cystatin C signaled hyperfiltration which is typical in early diabetes mellitus and significantly contributes to the progression of overt diabetic nephropathy." (PMID 22900035, 2012). "Participants with higher concentrations of cystatin C were more likely to be older, to have diabetes and hypertension, and to use antihypertensive medications." (PMID 21977320, 2011).
diabetes (continued). "Preliminary data strongly suggest that a combination of cystatin C and serum creatinine also improves the monitoring of kidney function in patients with diabetes mellitus." (PMID 19555481, 2009). "In the non-DM (non-diabetes mellitus) group, cumulative Cystatin C increased the risk of cognitive decline." (PMID 41778039, 2026). "In 4,029 individuals (mean age 72 ± 5.0 years, 59.6% female), serum cystatin C, depression, diabetes, educational attainment, forced expiratory volume in 1 s, and income were more associated with frailty than age and selected for inclusion in the AGELESS Score." (PMID 41426610, 2025). "The clinical value and cost-effectiveness of measuring plasma cystatin C in addition to routine serum creatinine assays in a subgroup of people with diabetes who may be perceived as having a homogeneously relatively good prognosis needs to be established." (PMID 40257600, 2025). "In addition, plasma cystatin C concentrations are increased in obesity, potentially confounding eGFRcyst measurement in diabetes given that it is a frequent comorbidity." (PMID 40257600, 2025). "In this large, community-based population, a negative eGFRdiff—where cystatin C-based eGFR is substantially lower than creatinine-based eGFR—is associated with a higher prevalence of diabetes, independent of overall kidney function." (PMID 41280371, 2025). "Studies also suggested that cystatin C is a better biomarker to reflect the diabetes status." (PMID 41280371, 2025). "In the Action to Control Cardiovascular Risk in Diabetes-Memory in Diabetes (ACCORD-MIND) study, which included subjects with diabetes, microalbuminuria and elevated cystatin C levels were significantly correlated with poor performance in verbal memory and executive function, respectively." (PMID 40979705, 2025). "Cystatin C levels were shown to be elevated in patients with a longer diabetes duration (696 and 726 ng/ml) for patients with a duration of 5–10 or > 10 years respectively compared to patients with a diabetes duration < 5 years (605 ng/ml; P < 0.001)." (PMID 38932813, 2024). "Additionally, urinary excretion of Cystatin C is elevated early in diabetes and prediabetic nephropathy and it suggests tubular injury." (PMID 39011442, 2024). "Cystatin C levels were elevated in patients with diabetes duration longer than 5 years (P < 0.001)." (PMID 38932813, 2024). "When investigating FGF21, Cystatin C, lipocalin-2, and MMP-9 in this study from diagnosis of type 1 diabetes over time, Cystatin C showed most promising results with increased values from diagnosis to follow-up and inverse correlation to HbA1c and duration of diabetes." (PMID 38932813, 2024). "Compared with the highest creatinine-cystatin C ratio group, the lowest creatinine-cystatin C ratio group had a 2.6-fold higher risk of DWFG, even after adjusting for potential confounding factors, including age, sex, diabetes mellitus, eGFR, and serum albumin." (PMID 38263396, 2024). "There was a positive correlation between anti-NC titers, age, and several conditions found in patients with metabolic syndrome such as high BMI, dyslipidemia, diabetes, and increased cystatin C plasma concentration as an indicator for reduced glomerular filtration rates." (PMID 36875076, 2023). "However, there are also studies demonstrating that oxidative stress can induce the synthesis of mRNA and protein of cystatin C, which is key pathogenetic component of the diabetes." (PMID 37056689, 2023). "Nevertheless, our findings further showed that eGFR based on cystatin C or a combination of creatinine and cystatin C was more predictive of mortality risk than eGFRcr regardless of diabetes status." (PMID 37128173, 2023). "In addition, an increase in cystatin-c level was seen with individuals with longer history of diabetes." (PMID 37002266, 2023).